CCL2 (C-C motif chemokine ligand 2)
Diseases named in the same sentence as CCL2 in open-access papers (continued):
Sharing a sentence is not in itself a finding about the gene and the disease.
cancer (continued). "The reason why cancers preferentially metastasize to lung, liver, bone and brain may be due to the presence of CCL2 and CCR2 in these tissues and organs 43, which are chemotactic for TM2 and thus, provides ideal conditions for harboring TM2." (PMID 38356723, 2024). "Additionally, a significant increase in cancer cell proliferation compared to that in the untreated control group was observed after treatment with 100 ng/ml CCL2." (PMID 38825648, 2024). "CCL2, secreted by cancer cells or CAFs, recruit monocytes, MDSCs, and Treg into TME." (PMID 38707901, 2024). "However, studies have shown that interrupting a treatment with a CCL2-targeting agent in mouse tumor models leads to the accumulation of monocytes and the promotion of cancer growth, which highlights the importance of prolonged drug administration." (PMID 39409110, 2024). "The CCR2 ligand, CCL2, is secreted by cancer cells via the autocrine/paracrine pathway." (PMID 39595209, 2024). "CCL2 is able to promote cancer cell growth and proliferation through various mechanisms." (PMID 38533503, 2024). "Strategies to target CCL2/CCR2 axis as cancer therapy are under investigation." (PMID 39199652, 2024). "Additionally, Additionally, CCL2 released by M2 macrophages activates β-catenin, enhancing cancer stemness and promoting the EMT process in TNBC." (PMID 39286635, 2024). "Further research into the specific roles of CCR2 and CCL2 in different cancer types and stages of disease progression is crucial for developing effective treatments that can modulate these pathways to benefit cancer patients." (PMID 39201480, 2024). "CCL2-overexpressing mice also had an increased susceptibility to DMBA-induced mammary tumors, demonstrating a relationship between macrophages, ECM density, and cancer risk." (PMID 39555068, 2024). "Moreover, one study has illustrated that CCL2 is essential for NK cell recruitment, providing an insight into the design of effective NK cell-based therapies for cancer." (PMID 38057698, 2023). "CCL2, an important chemokine for macrophage, is highly expressed in and secreted by cancer cells." (PMID 37915048, 2023). "Next, we asked whether CCL2, secreted by neural cells, affects the cytoskeletal mediators of migration in cancer cells." (PMID 37607005, 2023). "CCL2 plays a vital role in activating and recruiting macrophages in cancer progression." (PMID 37893029, 2023). "Therefore, we conclude that type I IFN signaling enhances the expression of CCL2 in cancer-activated astrocytes." (PMID 37149684, 2023). "This seemingly suggests that CCL2 may also have potential predictive value in immunotherapy response in these cancers." (PMID 38057698, 2023). "CCL2 is associated with immune tolerance and recruitment of suppressive immune cells such as myeloid derived suppressor cells (MDSC) and regulatory T cells (Tregs) in cancer; these cells are also implicated in graft survival." (PMID 37371745, 2023). "Moreover, Naph retains its inhibitory potential against chemotaxis of IMs toward CCL2–expressing cancer cells and the surrounding stromal cells, thereby reducing the expression of E-selectin in metastatic lung cancers without marked adverse effects." (PMID 36831085, 2023). "Moreover, CCL2 can support cancer cell motility, proliferation, survival, and the epithelial–mesenchymal transition (EMT)." (PMID 37373025, 2023). "In total, nine inflammation and cancer-associated DEGs were selected to show their changed expression patterns, comprising four up-DEGs (ADM, FSTL3, SPDEF, and SPNS2) and five down-DEGs (TACSTD2, CCL2, EDIL3, FAM20C, and OLFML2A)." (PMID 37953789, 2023). "Therefore, the regulation of CCL2 by CTNNAL1 is thought to be related to immune cells as well as the malignancy of cancer cells." (PMID 37239133, 2023).
cancer (continued). "Furthermore, significant positive correlations were observed among VEGF-A and three cytokines, such as CCL2, IL-6, and IFN-γ, and a positive association between IL-6 and IFN-γ within the Cancer TIF1-γ-DM group." (PMID 36357631, 2023). "Also increased by HFD but less so by the cancer cells was Ccl2 in contrast to its receptor Ccr2 that was modestly increased by the HFD but highly upregulated in the cancer groups." (PMID 38264656, 2023). "It will also be important to consider using them with other treatments, including surgery, radiation and anticancer drugs, although necrotic cancer cells may induce inflammatory responses and upregulate CCL2 production." (PMID 37208442, 2023). "Importantly, it has been reported that CCL2 can promote the development and progression of many types of cancers by directly and indirectly stimulating cancer cell migration through the regulation of MMPs." (PMID 37893141, 2023). "Cancer-derived TGF-α upregulates CCL2 expression in pancreatic nerves." (PMID 37607005, 2023). "The upregulation of plasma levels of VEGF-A, TNF-α, CCL2, IL-6, and IFN-γ in Cancer TIF1-γ-DM patients could provide insight into the underlying mechanism of the pathogenesis of Cancer TIF1-γ-DM." (PMID 36357631, 2023). "Some cancer patients have frequently upregulated serum and plasma CCL2 levels." (PMID 36357631, 2023). "Patients overexpressing CCL2 in cancer presented a worse prognosis." (PMID 38204755, 2023). "However, CCL2 expression was significantly associated with human TRAIL and TRAIL-R expression in both cancer types." (PMID 37605148, 2023). "Cancer cells can secrete both monocyte and macrophage chemotactic factors, e.g., C-C motif chemokine ligand 2 (CCL2), as well as the agents that accelerate the maturation of these cells and activate them, e.g., the colony stimulating factor 1 (CSF1) and CSF2, and also inhibit their chemotaxis." (PMID 38001676, 2023). "As the TAM phenotype plays a vital role in the tumor microenvironment, the inhibitory effect of Luteolin on the monocyte recruitment and migration of cancer cells via suppression of the TAM-secreted CCL2 was suggested as a novel therapeutic strategy for cancer." (PMID 36992138, 2023). "MΦs have been demonstrated to promote cancer progression through CCL2." (PMID 37792212, 2023). "In addition, CCL2 can have antitumorigenic and antimetastatic activity depending on cellular context and cancer type by regulating neutrophil activity." (PMID 36374225, 2023). "While the importance of CCL2/CCR2 signaling in macrophages during cancer progression is well documented, HtrA2 may regulate macrophage recruitment." (PMID 36704205, 2023). "Therefore, CCL2 neutralization limits metastases not only through its effects on premetastatic niches but also by limiting cancer cell intravasation at the primary site." (PMID 37208442, 2023). "The expression of STING in the normal lung tissues, as well as the dynamic changes of circulating CCL2, could serve as predictive biomarkers of symptomatic RP in cancer patients receiving thoracic radiotherapy." (PMID 37667317, 2023). "In addition to this classical neurotrophic molecule, we demonstrated that CCL2 derived from DRG neurons activates the cancer cell cytoskeleton through the CCR4 receptor and the entailing paxillin phosphorylation." (PMID 37607005, 2023). "However, interruption of CCL2 inhibition leads to an unexpected influx of monocytes from the bone marrow, which enhances cancer cell metastases and accelerates death in mouse models of metastatic breast cancer." (PMID 37706196, 2023). "This latter event was dependent on the secretion of mtROS and MCP1/CCL2 by preadipocytes and seems also to depend on the establishment of a burst of mtROS in cancer epithelial cells, which may be triggered by MCP1/CCL2 and other soluble factors." (PMID 37107188, 2023). "CCL2 was detected in the parenchyma in 15 of 27 (56%) ductal carcinomas." (PMID 37208442, 2023).
cancer (continued). "Similarly, the upregulation of CCL2 has been reported in docetaxel and cabazitaxel-resistant cancer cells." (PMID 36077785, 2022). "A recent review summarizes dual protumoral or antitumoral role of CCL2, that may depend on the interaction between cancer and immune cells." (PMID 36923280, 2022). "Conversely, stromal cells such as macrophages secrete more CCL-2 into the TME than cancer cells." (PMID 35741603, 2022). "Reciprocally, cancer cells produce CCL2 and GM-CSF which promote MФ recruitment." (PMID 36189323, 2022). "A variety of chemokines have been reported to be associated with cancer resistance, such as C-X-C chemokine ligand-8 (CXCL8), CC chemokine ligand-5 (CCL5), CC chemokine ligand-20 (CCL20), and CC chemokine ligand-2 (CCL2)." (PMID 36077785, 2022). "Therefore, lowering the expression level of CCL2 is likely to play a vital role in cancer suppression." (PMID 36238299, 2022). "Notably, HLA-I– cancer cells acquiring a mesenchymal status were associated with enhanced mRNA levels of the IFN-stimulated genes IFIT1, IFIT2, IFIT3, IFI6, IFI27, and CCL2." (PMID 35503263, 2022). "In conclusion, the mechanisms of CCL2 in inducing drug resistance in cancer are very complicated, and further pre-clinical studies and clinical trials should be considered to investigate whether targeting CCL2 could overcome anticancer drug resistance." (PMID 36077785, 2022). "Mechanistic studies showed that treatment of fibroblasts with viral product-containing exosomes promoted the characteristics of cancer-associated fibroblasts by stimulating YAP1 signaling and the production of the immunosuppressive cytokines IL8, CCL2, and IL6." (PMID 35986369, 2022). "In this context, patients with cancer are characterized by a catabolic state, with increased skeletal-muscle-protein turnover, which might explain the significant changes in CCL2 expression found in our study." (PMID 35158762, 2022). "One of the most potent factors involved in this process is CCL2, upregulated in many cancers." (PMID 35202089, 2022). "Similarly, this pathway was also shown to be involved in the recruitment of type I cytotoxic γδ T cells in melanoma tumors, a hybrid NK/CD8 T lymphocyte able to kill cancer cells, thus conferring an antitumor role of CCL2/CCR2." (PMID 36429101, 2022). "These cells are also able to activate CD8+ cytotoxic T cells, which are the most potent anticancer immune effectors and constitute the foundation of current effective cancer immunotherapies through the secretion of the chemokines previously listed (CCL2, CCL3, CCL4, CCL5 and CXCL10)." (PMID 36325334, 2022). "Thus, the level of CCL2 is increased in breast, liver, and endometrial cancers and reduced in colorectal, lung, kidney, urothelial, and other cancers." (PMID 36286054, 2022). "High levels of CCL2 have also been shown to correlate with high cancer occurrence in several cancer types, suggesting Gli3 may play a role in cancer in addition to pathogen-induced inflammation." (PMID 35937499, 2022). "The elevated monocyte numbers can be either caused by an increased monopoiesis or an enhanced mobilization from the bone marrow by CCL2, which is often elevated in serum of cancer patients, arguing for the involvement of the bone marrow compartment in cancer patients." (PMID 36257966, 2022). "Eight cytokines (IL-1β, IL-6, IL-10, TGF-β, CCL2, CXCL8, CSF-1, and VEGF) were identified to have higher expression values in the high-risk group than in the low-risk group, which was relevant to the progression, invasion, and metastasis of cancers." (PMID 36120553, 2022). "Through MMP9, TAMs activate CCL2 expression in cancer cells." (PMID 36268282, 2022). "Therefore, the nerve-released CCL2 interacts with cancer cell CCR2 to promote PNI and this CCR2-mediated signaling links to the MAPK and Akt pathway activity." (PMID 36077602, 2022).
cancer (continued). "In addition, in pre-malignant lesions, CCL2 produced by cancer cells and myeloid cells attracts CD206+/Tie2+ macrophages and induces Wnt-1 upregulation that, in response, downregulates E-cadherin junctions in the HER2+ early cancer cells." (PMID 35892884, 2022). "A comprehensive understanding of the role and mechanism of CCL2 in anticancer drug resistance may provide new therapeutic targets for reversing cancer resistance." (PMID 36077785, 2022). "CCL2 has been suggested as a potential biomarker for several types of cancer, including prostate." (PMID 35053602, 2022). "Furthermore, previous studies suggest that the expression of CCL2 has a strong relationship with cancer prognosis." (PMID 36403055, 2022). "The invasive effects of MMP13 on cancer cells can be mediated through six novel targets, including the inactivation of chemokine C-C motif ligand 2 (CCL2) and CCL7, activation of platelet-derived growth factor-C (PDGF-C) and cleavage of SAA3, osteoprotegerin (OPG), CutA and antithrombin III." (PMID 35884405, 2022). "Several studies have reported a correlation between CCL2 expression and malignant events in cancer." (PMID 35715860, 2022). "MiR-375 is released by apoptotic BC cells and stimulates the production of CCL2 in other cancer cells by unknown mechanisms." (PMID 35202089, 2022). "A recent elegant study demonstrates that, in basal-like BC, Notch not only regulates cancer cell expression of the mononuclear cell chemokines IL-1β and CCL2, but also facilitates TGF-β-mediated activation of tumor cells by TAMs, closing a signaling loop between these two cell types." (PMID 35682974, 2022). "As CCL2/CCR2 activated SRC and SRC interacts with MET to regulate receptor activation in carcinoma cells, we asked whether CCL2-mediated SRC activation was important for MET phosphorylation." (PMID 35405500, 2022). "Therefore, we sought to further evaluate the relative CCL2 contribution of carcinoma cells and CAFs." (PMID 36256464, 2022). "Notably, monocytes utilize CCR2 to infiltrate into PDA, where CCL2 is secreted by carcinoma cells and to a larger degree by multiple CAF phenotypes." (PMID 36256464, 2022). "Despite the setbacks in development of CCL2/CCR2 in clinical studies, particularly for inflammatory conditions, the detrimental roles of the CCL2/CCR2 axis in cancer setting have increasingly been appreciated so that the CCL2/CCR2 axis remains to be actively targeted as candidates for immunotherapy." (PMID 34804061, 2021). "CCL2 is overexpressed in various cancers including glioma, prostate and breast cancers." (PMID 33888841, 2021). "Considering the important role of CCL2 in cancer progression, we focused on CCL2 for further study." (PMID 34729117, 2021). "Additionally, cancer-cell-derived CCL2, CCL18, CCL17 and CXCL4 work in concert to polarize macrophages towards M2-like phenotypes." (PMID 34638388, 2021). "Additionally, increased MDSCs in the peripheral blood and cancer tissue of ccRCC patients had a positive correlation with CCL2 expression." (PMID 34445235, 2021). "CCL2 secreted by cancer cells or CAFs mobilizes monocytes, MDSCs, and Treg into TME." (PMID 34445235, 2021). "CCL2 recruits monocytes to the sites of the immune microenvironment produced by cancer tissues." (PMID 34525267, 2021). "The increased level of CCL2 is associated with metastasis of many cancers and is a negative prognostic factor for several cancer types." (PMID 33919517, 2021). "Indeed, in the mammary PyMT model, newly tumor-infiltrated blood CCR2+ monocytes are recruited by cancer cell– and stromal cell–derived CCL2." (PMID 33783686, 2021). "Therefore, CCL2 and CCR2 enable us to explore the sophisticated mechanisms underlying cancer development and provide potential options for treating malignant tumours." (PMID 34464477, 2021).
cancer (continued). "In addition, Statins restrict tumor cell growth by inhibiting CCL3 secreted by cancer cells and IL-6 and CCL2 produced by MSC, thereby disrupting the communication between cancer cells and MSC." (PMID 34858839, 2021). "CCL2 blockade was reported to significantly enhance vaccine-mediated cancer immune response." (PMID 34386431, 2021). "The CCL2/CCR2 axis may represent a unique opportunity for anti-cancer therapy and work in this area is already being explored." (PMID 34353349, 2021). "In a study with human liver CAFs and cancer lines, CAFs could up-regulate CCL2 expression in cancer cells." (PMID 34804061, 2021). "CCR2+ cancer cell invasiveness was enhanced by fibroblast-derived CCL2 via SRC and PKC activation." (PMID 34386431, 2021). "Moreover, one of the main mechanisms found in different types of cancer, including BC, is the secretion of CCL2 through which the cancer cells are able to attract and increase the TAM abundance into the TME." (PMID 33777750, 2021). "Among the many SASP factors, IL-6, CCL5, CXCL12, CCL2 and IL-8 have a particularly important role in supporting cancer cell metastasis formation and the establishment of an immunosuppressive microenvironment, although in some cancer models they can be found in the immune stimulatory secretome." (PMID 34079557, 2021). "CCL2 promotes angiogenesis and supports the progression of malignant tumors." (PMID 34445235, 2021). "Consequently, CCL2 and CCR2 enable us to explore the sophisticated mechanisms underlying cancer development and provide potential options for treating malignant tumours." (PMID 34464477, 2021). "Therefore, we demonstrate that IL1A-induced CCL2 and IL8 expression directly or indirectly associated with cancer metastasis in TNBC cells." (PMID 34203721, 2021). "CCL2+ myeloid cells are de-differentiated to macrophages, engulf cancer cells, and clear them out." (PMID 34746270, 2021). "Moreover, CCL2 promoted cancer cell to achieve self‐renew and reproduce by activating a series of signal transduction pathways downstream of GPCRs." (PMID 34464477, 2021). "Additionally, by stimulating cancer cells to release inflammatory chemokines (CCL2 or CCL20), IL-17A-producing cells can enhance CD1a+ DC infiltration of the TME, which is correlated with favorable OS of patients with ESCC." (PMID 33995371, 2021). "In a mouse model, stress-loaded norepinephrine suppresses blood CCL2 levels and macrophage infiltration into cancer tissues, and β-epinephrine receptors may be targets for melanoma treatment." (PMID 34445235, 2021). "CCL2, as an important adipokine, mediates crosstalk between cancer cell and adipocytes." (PMID 34386431, 2021). "Hence, FAP and CCL2 can be therapeutic targets because FAP develops cancer by activating CAF STAT3/CCL2 signaling." (PMID 34445235, 2021). "CCL2, already mentioned, may play a role in the docetaxel resistance in cancer through the activation of the PI3K/AKT pathway and inhibition of apoptosis." (PMID 34948097, 2021). "Meanwhile, ATF3 is also important for the colonization of the cancer cells in the metastatic sites in the lung through prompting expression of chemokine C-C motif ligand 2 (CCL2) that recruits inflammatory monocytes and VEGFR1+ macrophages that favor metastasis and immunosuppression." (PMID 35052581, 2021). "CCL2 secreted by cancer cells also has direct cancer-promoting effects." (PMID 34445235, 2021). "All these data suggest that the CCL2/CCR2 axis could be a promising target for cancer treatment and prevention." (PMID 34356595, 2021). "As we highlighted above some aspects of how to target CCL2/CCR2 in cancer, we also contend that combination therapy may broaden and improve application of CCR2 antagonism as cancer therapy." (PMID 34804061, 2021). "Moreover, the expression of Ccl2 was significantly increased in sorted E-BCSCs (ALDH+ cancer cells) compared with the unsorted bulk 4T1 cells." (PMID 34178639, 2021).